GLT1D1 (glycosyltransferase 1 domain containing 1)
Synonyms: FLJ31978
Tractability: Antibody: UniProt places it where antibodies can reach, with high confidence; UniProt predicts a signal peptide or a membrane-spanning region; its Gene Ontology location is reachable by antibodies, with medium confidence.
Gene: Protein-coding gene on chromosome 12 (128,853,427 to 128,984,968, forward strand). Ensembl gene ENSG00000151948.
Subcellular location: Secreted
Subcellular location (Human Protein Atlas): Cytosol; Predicted to be secreted
Gene Ontology:
Molecular function: glycosyltransferase activity
Cellular component: cytosol; extracellular region
Genetic constraint (gnomAD): Loss-of-function variants: 9 observed, 15.74 expected, observed/expected ratio (o/e) 0.57, 90% interval 0.34 to 1. The upper end of that interval is the gene's LOEUF score, 1, which puts it in group 4 of 6, group 1 being the genes least tolerant of losing a copy. Missense variants: 228 observed, 222.24 expected, observed/expected ratio (o/e) 1.03, 90% interval 0.92 to 1.14. Synonymous variants: 107 observed, 85.46 expected, observed/expected ratio (o/e) 1.25, 90% interval 1.07 to 1.47.
Homologues: Orthologues: chimpanzee GLT1D1 (99% identical), pig GLT1D1 (85% identical), mouse Glt1d1 (84% identical), rat Glt1d1 (83% identical), dog GLT1D1 (81% identical), macaque GLT1D1 (78% identical), tropical clawed frog glt1d1 (59% identical), zebrafish glt1d1 (53% identical). Paralogues in human: ALG11 (18% identical), ALG2 (17% identical), PIGA (15% identical).
Diseases named in the same sentence as GLT1D1 in open-access papers:
GLT1D1 is named in the same sentence as 17 diseases in open-access papers, as found by Europe PMC text mining. Sharing a sentence is not in itself a finding about the gene and the disease. The quoted sentences say what the papers report.
B-cell non-Hodgkin lymphoma (6 papers, 2020 to 2026). The most common type of non-Hodgkin lymphoma. "GLT1D1 expression is positively correlated with glycosylated PD-L1 levels in B-cell non-Hodgkin’s lymphoma, and high GLT1D1 expression is associated with poor prognosis of patients." (PMID 36561746, 2022). "Analysis of clinical specimens revealed that GLT1D1 expression was positively correlated with the level of glycosylated programmed cell death‐ligand 1 (PD‐L1) in B‐cell NHL and that high GLT1D1 expression was associated with poor prognosis." (PMID 32157792, 2020). "Glycosyltransferase 1 domain-containing 1 (GLT1D1) facilitates the transfer of N-linked glycans to PD-L1, promoting tumor immune evasion in B-cell non-Hodgkin’s lymphoma." (PMID 41486149, 2026). "We then examined the expression of GLT1D1 in the 3 subtypes of B‐cell NHL cell lines by qRT‐PCR and western blot." (PMID 32157792, 2020). "Considering the facts that glycosylation of PD‐L1 by N‐glycosyltransferease can stabilize PD‐L1 protein and that GLT1D1 expression is associated with poor prognosis in NHLs, we investigated whether GLT1D1 could induce immunosuppression through glycosylation and stabilization of PD‐L1 in B‐cell NHLs." (PMID 32157792, 2020). "A coculture system was used to test the effect of siRNA knockdown of GLT1D1 in B‐cell lymphoma on the functions of activated T cells." (PMID 32157792, 2020). "To this end, we first used CRISPR‐Cas9 technology to knockout GLT1D1 in mouse B‐cell lymphoma cells (A20 cell line) and tested cell survival in culture and tumor formation in vivo." (PMID 32157792, 2020). "Glycosyltransferase 1 containing domain 1 (GLT1D1) is highly upregulated in incurable B-cell non-Hodgkin’s lymphoma subtypes and early relapsed diffuse large B-cell lymphoma and may be associated with poor prognosis of colon cancer and multiple myeloma." (PMID 36561746, 2022). "Our work has identified GLT1D1 as a predictive biomarker for B‐cell NHL." (PMID 32157792, 2020). "Using a RT‐PCR array analysis, we have identified that glycosyltransferase 1 domain‐containing 1 (GLT1D1), an enzyme that transfers glycosyl groups to proteins, is highly upregulated in the incurable subtype of B‐cell NHL and in early relapse diffuse large B‐cell lymphoma." (PMID 32157792, 2020). "Since N‐linked glycosylation (N‐glycosylation) of PD‐L1 is essential for maintaining PD‐L1 protein stability and its immune checkpoint function, we asked whether GLT1D1 promoted PD‐L1 N‐glycosylation in B‐cell NHL cells." (PMID 32157792, 2020). "In B-cell non-Hodgkin lymphoma (B-NHL), glycosyltransferase 1 domain-containing 1 (GLT1D1) enhances the stability of PD-L1 through N-glycosylation, thereby promoting immunosuppression and tumor growth, and is a potential target for B-NHL treatment." (PMID 38725856, 2024). "Targeting PD-L1 glycosylation with monoclonal antibodies or the glycosyltransferase GLT1D1 (glycosyltransferase 1 domain containing 1) has been found to enhance tumor immune response in TNBC and B cell lymphoma, respectively." (PMID 34503236, 2021). "To test the cause–effect relationship between GLT1D1 expression and glycosylation of PD‐L1, we transfected B‐cell lymphoma lines (Raji and JVM2) with relatively high level of GLT1D1 with siRNA against GLT1D1 and then analyzed glycosylated PD‐L1." (PMID 32157792, 2020). "Consistent results were obtained with another coculture system using activated CD8+ T lymphocytes and B‐cell NHL line (JVM2) with or without GLT1D1 knockdown." (PMID 32157792, 2020).
colorectal cancer (3 papers, 2016 to 2022). A primary or metastatic malignant neoplasm that affects the colon or rectum. "First, GLT1D1 around rs7300146 has been known as a candidate oncogene of colorectal cancer and relapse marker of multiple myeloma." (PMID 29967481, 2018).
lymphoma (3 papers, 2020 to 2024). A malignant (clonal) proliferation of B- lymphocytes or T- lymphocytes which involves the lymph nodes, bone marrow and/or extranodal sites. "The DLBCL patients with poor prognosis (n = 5) had significant upregulation of GLT1D1 compared to those with good prognosis (n = 30) (P < 0.001), suggesting that overexpression of GLT1D1 is associated with poor prognosis in lymphoma." (PMID 32157792, 2020). "Downregulation of GLT1D1 decreased the glycosylated PD‐L1 protein and promoted cytotoxic T‐cell function against lymphoma cells." (PMID 32157792, 2020). "Our data analysis also revealed that GLT1D1 was positively correlated with PD‐L1 expression in lymphoma." (PMID 32157792, 2020). "Downregulation of GLT1D1 resulted in a decrease of glycosylated PD‐L1 and enhanced cytotoxic T‐cell function against lymphoma cells." (PMID 32157792, 2020). "We showed that GLT1D1 was significantly upregulated in incurable lymphoma (MCL) and in a subset of DLBCL patients with poor prognosis, suggesting that high expression of GLT1D1 may predict high risk of lymphoma relapse, likely due in part to immunosuppression." (PMID 32157792, 2020). "As such, targeting GLT1D1 could be a novel strategy to combat PD‐L1/PD‐1 interaction‐mediated immunosuppression in B‐NHLs and could potentially increase the clinical outcome of lymphoma patients." (PMID 32157792, 2020). "We were unable to recover any viable GLT1D1‐knockout A20 cells, since the sgGLT1D1‐targeted A20 cells lost their ability to survive in culture, suggesting GLT1D1 might be required for the survival of the lymphoma cells." (PMID 32157792, 2020). "To further evaluate the relationship between GLT1D1 and PD‐L1 in human DLBCL patients, we analyzed the correlation between GLT1D1 expression and glycosylated PD‐L1 in lymphoma patient tissues." (PMID 32157792, 2020).
systemic lupus erythematosus (3 papers, 2018 to 2019). An autoimmune multi-organ disease typically associated with vasculopathy and autoantibody production. "In a systemic lupus erythematosus (SLE) Korean cohort with 781 patients, a hybrid approach with a GWAS array and Immunochip genotyping allowed for the sensitive detection of two SLE risk loci, XKR6 and GLT1D1, which were found to be significantly higher in childhood-onset SLE." (PMID 31231652, 2019).
hepatocellular carcinoma (1 paper, 2022). A malignant tumor that arises from hepatocytes. "Besides, GLT1D1 is a tumor suppressor gene and is highly expressed in hepatocellular carcinoma." (PMID 35456988, 2022).
melanoma (1 paper, 2020). A malignant, usually aggressive tumor composed of atypical, neoplastic melanocytes. "We then used mouse B16 melanoma cells as an alternative model for the GLT1D1 knockout study." (PMID 32157792, 2020).
xerostomia (1 paper, 2022). Dryness of the mouth resulting from reduced salivary secretion. "GLT1D1 was also associated with higher risk of reporting moderate to severe xerostomia." (PMID 35459784, 2022). "The most prominent findings in our study included potential associations of ANTXR1, RTP1, GLT1D1, NLRP9, and EGFLAM genes with xerostomia." (PMID 35459784, 2022).
tumor (8 papers, 2020 to 2026). "Downregulation of GLT1D1 caused a decrease in glycosylated PD‐L1 protein, leading to an increase in cytotoxic T‐cell infiltration in the tumor microenvironment." (PMID 32157792, 2020). "High expression of GLT1D1 increases PD- L1 glycosylation and promotes tumor immune escape and tumor growth." (PMID 37554324, 2023). "In vivo, overexpression of GLT1D1 promoted tumor growth by facilitating tumor immune escape through increased levels of PD‐L1." (PMID 32157792, 2020). "We next evaluated the role of GLT1D1 in maintaining cell viability in vitro and tumor growth in vivo." (PMID 32157792, 2020). "Clone #2, which expressed a similar level of GLT1D1 as the parental cells, showed similar tumor growth and comparable PD‐L1 expression and CD8+ T‐cell infiltration as the control xenograft." (PMID 32157792, 2020). "GLT1D1 and glycosylated PD‐L1 protein levels were analyzed in the tumor tissues from 15 DLBCL patients (5 patients with poor prognosis and 10 patients with good prognosis)." (PMID 32157792, 2020). "These might partially explain our findings that low infiltrating CD8+ T cells in the tumor xenografts of Clone 1# cells, which expressed very high levels of GLT1D1 and glycosylated PD‐L1." (PMID 32157792, 2020). "We further demonstrated that GLT1D1 could promote the N‐glycosylation level of PD‐L1 and impair the cytotoxic T‐cell function against tumor cells." (PMID 32157792, 2020). "Notably, clone 1# xenograft, which expressed high level of GLT1D1, exhibited a significant increase in tumor growth, associated with a high level of PD‐L1 expression and very few CD8+ T‐cell infiltration in the tumor tissues." (PMID 32157792, 2020).
cancer (2 papers, 2020 to 2024). A tumor composed of atypical neoplastic, often pleomorphic cells that invade other tissues. "As PD‐L1 glycosylation is essential for its stabilization and modulation of immune function, we reasoned that GLT1D1 could induce cancer immunosuppression by maintaining PD‐L1 protein glycosylation and stabilization." (PMID 32157792, 2020).
genetic disorders (1 paper, 2025). "Among the prioritized custom CMA genes in the smallest custom CMA NDDi, KIAA1586, ASCL3, BTNL3, SIRPB1, and GLT1D1 exhibit high average shortest path length and low proximity, indicating vulnerability to genetic disorders." (PMID 40869915, 2025).
GLT1D1 also shares sentences with these, for which no sentence is quoted: colon cancer (2 papers); non-Hodgkin lymphoma (2); breast carcinoma (1); diffuse large B-cell lymphoma (1); glycogen storage disease type II (1); ovarian carcinoma (1); Sepsis (1).